DYNC2I2 (dynein 2 intermediate chain 2)
Description:
Acts as one of several non-catalytic accessory components of the cytoplasmic dynein 2 complex (dynein-2 complex), a motor protein complex that drives the movement of cargos along microtubules within cilia and flagella in concert with the intraflagellar transport (IFT) system. DYNC2I2 plays a major role in retrograde ciliary protein trafficking and in ciliogenesis. Required also to maintain a functional transition zone. Acts as a negative regulator of the Toll-like and IL-1R receptor signaling pathways. Inhibits the MAP3K7-induced NF-kappa-B activation pathway. Inhibits MAP3K7 phosphorylation at 'Thr-184' and 'Thr-187' upon Il-1 beta stimulation.
Synonyms: WDR34; DIC5; MGC20486; bA216B9.3; FAP133; CFAP133; SRTD11
Tractability: Small molecule: a structure with a bound ligand is known. PROTAC: ubiquitination databases record sites on it.
Gene: Protein-coding gene on chromosome 9 (128,633,646 to 128,656,847, reverse strand). Ensembl gene ENSG00000119333.
Subcellular location: Cytoplasm; Cytoplasm, cytoskeleton, cilium basal body; Cytoplasm, cytoskeleton, cilium axoneme; Cytoplasm, cytoskeleton, microtubule organizing center, centrosome; Cell projection, cilium; Cell projection, filopodium
Subcellular location (Human Protein Atlas): Basal body; Centrosome; Nucleoplasm; Cytosol; Nuclear bodies; Nucleoli; Primary cilium
Pathways (Reactome):
Organelle biogenesis and maintenance: Intraflagellar transport
Gene Ontology:
Molecular function: dynein light chain binding; protein binding; dynein heavy chain binding
Biological process: cilium assembly; intraciliary retrograde transport; intraciliary transport
Cellular component: centrosome; ciliary basal body; cilium; cytoplasm; cytoplasmic dynein complex; cytosol; axoneme; centriole; ciliary plasm; ciliary tip; dynein complex; male germ cell nucleus; filopodium
Genetic constraint (gnomAD): Loss-of-function variants: 41 observed, 51.35 expected, observed/expected ratio (o/e) 0.8, 90% interval 0.62 to 1.04. The upper end of that interval is the gene's LOEUF score, 1.04, which puts it in group 4 of 6, group 1 being the genes least tolerant of losing a copy. Missense variants: 738 observed, 697.77 expected, observed/expected ratio (o/e) 1.06, 90% interval 1 to 1.12. Synonymous variants: 359 observed, 308.94 expected, observed/expected ratio (o/e) 1.16, 90% interval 1.07 to 1.27.
Gene-disease validity (ClinGen):
ClinGen rates the evidence that DYNC2I2 causes each of these diseases.
short-rib thoracic dysplasia 11 with or without polydactyly (autosomal recessive): Definitive.
Homologues: Orthologues: chimpanzee DYNC2I2 (99% identical), macaque DYNC2I2 (95% identical), dog DYNC2I2 (88% identical), rabbit DYNC2I2 (86% identical), pig DYNC2I2 (84% identical), rat Dync2i2 (83% identical), mouse Dync2i2 (83% identical), guinea pig DYNC2I2 (77% identical), tropical clawed frog dync2i2 (55% identical), zebrafish dync2i2 (47% identical). Paralogues in human: DYNC2I1 (22% identical), DYNC1I2 (19% identical), DNAI1 (19% identical), DNAI4 (19% identical), DYNC1I1 (18% identical), DNAI2 (18% identical), DNAI3 (18% identical).
Diseases named in the same sentence as DYNC2I2 in open-access papers:
DYNC2I2 is named in the same sentence as 13 diseases in open-access papers, as found by Europe PMC text mining. Sharing a sentence is not in itself a finding about the gene and the disease. The quoted sentences say what the papers report.
breast carcinoma (3 papers, 2021 to 2022). "For DYNC2I2 (also known as WDR34), an integrated bioinformatics study shows that high DYNC2I2 mRNA expression is correlated with shorter overall survival and relapse-free survival in breast cancer patients, which is consistent with our finding that DYNC2I2 could serve as a risky factor in TNBC." (PMID 34604090, 2021).
oral cancer (3 papers, 2020 to 2022). "DYNC2I2 is also found to play oncogenic roles in the progression of HCC, whereas it is shown as a tumor-suppressor molecule in human oral cancer." (PMID 34604090, 2021).
cervical cancer (1 paper, 2022). A primary or metastatic malignant neoplasm involving the cervix. "Finally, we identified that the model constructed by GIMAP4, GIMAP1, FGF13-AS1, EFEMP2, and DYNC2I2 could be used as the prediction model for the prognosis of cervical cancer." (PMID 35782114, 2022).
DYNC2I2 also shares sentences with these, for which no sentence is quoted: Jeune syndrome (6 papers); ciliopathy (5); short rib-polydactyly syndrome type III (2); tumor (2); anencephaly (1); colorectal cancer (1); retinal degeneration (1); retinal disease (1); Rod-cone dystrophy (1); short rib-polydactyly syndrome (1).